USP13 (ubiquitin specific peptidase 13)
Diseases named in the same sentence as USP13 in open-access papers (continued):
Sharing a sentence is not in itself a finding about the gene and the disease.
cancer (38 papers, 2016 to 2025). A tumor composed of atypical neoplastic, often pleomorphic cells that invade other tissues. "This is incompatible with the findings that USP13 can deubiquitinate diverse substrates implicated in human disease and various cancer." (PMID 36612196, 2022). "The linkage of USP13 to these PCa-related signaling pathways uncovers the underlying mechanisms of USP13 in cancers and provides solid evidence to support its role in facilitating AR activity." (PMID 36564767, 2022). "A deubiquitinating enzyme, Ubiquitin-specific Peptidase 13 (USP13), is known to be engaged in diverse cellular processes by regulating various important substrates implicated in disease and cancer." (PMID 36612196, 2022). "Previous studies have implicated USP13 deubiquitinase in cancer development by regulating protein stability of oncogenes or tumor suppressors." (PMID 29335437, 2018). "We sought to further investigate cancer-associated alterations of USP13 and MCL1 in more detail and determine the clinical relevance of USP13-MCL1 regulatory axis." (PMID 29335437, 2018). "Taken together, our results demonstrate that USP13 may be a causal factor and a therapeutic target of cancer cell response to chemotherapy." (PMID 28569838, 2017). "HCC patient-derived organoids (PDOs), HCC cell lines and animal models were utilized to evaluate the anti-cancer responses of USP13 inhibition." (PMID 41330897, 2025). "Among the DUBs, ubiquitin-specific protease 13 (USP13) has attracted attention due to its role in regulating cellular processes relevant to cancer progression." (PMID 41330897, 2025). "In ovarian cancer, 2-Met has demonstrated efficacy in promoting cancer cell death after replication stress by inhibiting USP13." (PMID 41330897, 2025). "Given its involvement in key cellular processes, USP13 represents a promising therapeutic target for cancer treatment, antiviral defense, and metabolic disorders." (PMID 41307804, 2025). "Data from cBioPortal showed that amplification of the USP13 gene is common in cancers, and the protein structure along with the phosphorylation, ubiquitination and methylation sites were also analyzed." (PMID 36564767, 2022). "The molecular function of USP13 in tumorigenesis has been controversial in different cancers according to previous studies." (PMID 35898882, 2022). "The prognostic role of USP13 across cancers was analyzed using Kaplan–Meier curves based on the TCGA database." (PMID 36564767, 2022). "USP13 expression was found to be positively correlated with the optimistic prognosis of 6 cancer types and poor prognosis of the other 10 cancer types." (PMID 36564767, 2022). "Aurora B phosphorylates USP13 at Serine 114, prompting their interaction between USP13 and Aurora, showing a potential direct link between abnormalities occurring during the cell cycle and USP13 in several human cancers." (PMID 36612196, 2022). "Collectively, dysregulation of USP13 in cancers is commonly observed, and the role of USP13 in tumorigenesis can be controversial according to different cancer types." (PMID 36564767, 2022). "We found that USP13 gene amplification is common in cancers, and USP13 significantly co-expressed with PIK3CA in PCa tissues." (PMID 36564767, 2022). "Overall, we uncovered a new mechanism for the regulation of USP13 stability via a post-translational modification, suggesting novel therapeutics targeting USP13 in USP13-amplified cancers." (PMID 36612196, 2022).
cancer (continued). "Whilst oncogenes can be upregulated in cancer at the transcriptional level, the transcriptional regulation of USP13 is poorly understood." (PMID 33627786, 2021). "Deubiquitinase USP13 is aberrantly expressed in several human cancers and correlates with poor prognosis." (PMID 33195243, 2020). "Because drug development specifically against MCL1 has been considerably slower, targeting USP13 to inhibit MCL1 indirectly is likely to represent an alternative approach to potentiate the therapeutic efficacy of ABT-263 in cancer cells." (PMID 29335437, 2018). "Frequent amplification of USP13 was also identified in 53 human OVCA cell lines from the Cancer Cell Line Encyclopedia." (PMID 27892457, 2016). "To determine the role of USP13 in glutamine-dependent reductive carboxylation for lipogenesis, we cultured cancer cells in [U-13C] glutamine medium." (PMID 27892457, 2016). "Further exploration of USP13’s broader regulatory mechanisms could advance precision therapies for angiogenesis-driven cancers." (PMID 40746889, 2025). "While the functions of USP13 have been extensively studied in various cancers, including gastric cancer, melanoma, ovarian cancer, cervical cancer, cholangiocarcinoma, glioblastoma, kidney cancer, and breast cancer, its role in CRC remains unclear." (PMID 41307804, 2025). "Although previous research has indicated that USP13 may influence cancer growth by regulating the stability of oncogenes and tumor suppressor proteins, its role in various malignancies remains inconsistent." (PMID 40746889, 2025). "Furthermore, the potential of USP13 or MKK3 as prognostic or predictive biomarkers for cancer treatment response necessitates additional validation using clinical samples and bioinformatics analyses." (PMID 41307804, 2025). "We first assessed the anti-cancer effect of the USP13 inhibitor 2-Met in HCC cells." (PMID 41330897, 2025). "For example, since 2015, several DUBs-targeted agents, including VLX1570 (targeting USP14), P22077 (targeting USP7/USP10/USP47), P5091 (targeting USP7/USP47), and spautin-1 (targeting USP10/USP13), have been investigated in the clinic to treat certain types of cancers." (PMID 39522000, 2024). "USP13 was involved in the occurrence and progression of cancer." (PMID 36639822, 2023). "In addition, data from the Human Cancer Metastasis Database (HCMDB) verified the upregulation of USP13 in OS specimens." (PMID 37151889, 2023). "USP13 promotes tumorigenic potential, cell invasion, and cell survival in different human cancers." (PMID 38093367, 2023). "Importantly, USP13 expression is positively correlated with cancer progression and predicts poor survival of SCLC patients." (PMID 35898882, 2022). "Importantly, the effects of USP13 on SCLC cancer stemness maintenance and lipogenesis were abrogated by FASN depletion." (PMID 35898882, 2022). "Hence, USP13 functions as a pivotal cancer silencer in most human cancers, including bladder cancer, melanoma and breast cancer." (PMID 36564767, 2022). "Since FASN is a key enzyme involved in USP13-promoted cancer stemness, we further examined whether FASN inhibitor could be a favorable treatment strategy." (PMID 35898882, 2022). "However, there have been some literatures illustrating controversial roles of USP13 in different kinds of cancers, which is discussed in later sections." (PMID 36188217, 2022). "In addition, cancer cell metabolism or some other mechanism driven by USP13 that would increase sensitivity to paclitaxel." (PMID 35173307, 2022). "Thus, dysregulation of USP13 can give rise to the occurrence and development of plenty of diseases, in particular malignant tumors." (PMID 35445009, 2022). "Having discovered the cancer-driven potential of USP13 in PCa, we then sought to determine whether there is an effective inhibitor of USP13 to suppress its oncogenic functions." (PMID 36564767, 2022).
cancer (continued). "Therefore, we examined a combinatory effect of ATK inhibition and USP13 inhibition on USP13-overexpressing PTU cancer cells." (PMID 35173307, 2022). "Hence, we performed a pan-cancer analysis to evaluate the expression of USP13 in different cancer types based on the TCGA database." (PMID 36564767, 2022). "To test this, we used CRISPR-mediated gene editing to introduce biallelic inactivating mutations into USP13 in both HCT116 cells and HeLa cells (see Experimental Procedures for details), two human cancer cell lines with wildtype cohesin genes, and intact sister chromatid cohesion." (PMID 33334891, 2021). "Additionally, kinase Aurora B induced phosphorylation of the Ser114 residue in USP13 prevents several major human cancers by promoting its interaction with partners and stability." (PMID 34177595, 2021). "There have been several studies suggesting that the regulatory role of USP13 in human cancer could be controversial." (PMID 31200745, 2019). "However, the pathological function of USP13 in tumourigenesis has been controversial in different cancers." (PMID 29335437, 2018). "Furthermore, USP13 was downregulated in both cancer and healthy tissues." (PMID 38303549, 2024). "Therefore, more investigations are warranted to broaden the profiles of USP13 in cancers." (PMID 36188217, 2022). "Moreover, incubation with USP13 inhibitor spautin-1 reduces survival of OVCA cell lines after replication stress inducing agents, implying that the development of selective USP13 inhibitors is feasible for treatment of these patients of conventional cancer chemotherapy." (PMID 35445009, 2022). "However, further studies revealed that USP13 may have context-dependent functions in cancer development by interacting with different substrates to regulate protein stability." (PMID 35898882, 2022). "Furthermore, following treatment of Spautin-1 in conjunction with Olaparib, effects on OVCA models are remarkably enhanced, indicating that USP13 may be applied to overcome the chemotherapy resistance of cancer cells." (PMID 35445009, 2022). "Various combinations of PTMs on USP13 may result in diverse effects by altering its cellular localization, deubiquitinase enzymatic activity, or substrate specificity of USP13 in a different context of cancers." (PMID 36612196, 2022). "Therefore, it may be possible that USP13 overexpression could increase cancer stemness, which also could increase cisplatin resistance." (PMID 35173307, 2022). "Likewise, USP13 exerts an antitumor role in several types of cancers." (PMID 35445009, 2022). "Developing USP13 inhibitors may provide novel insights into cancer therapy." (PMID 36188217, 2022). "Moreover, ATM-induced phosphorylation of the Thr196 residue in USP13 after DNA damage functions as an essential regulatory event, and plays a critical role in the resistance of cancer cells to chemotherapy by deubiquitinating RAP80, promoting recruitment of complexes, and eliciting a DDR." (PMID 34177595, 2021). "Therefore, the researchers proposed that ACLY may play an important role in the USP13-mediated deubiquitination to promote cancer development." (PMID 33194756, 2020). "The expression of USP13 in cancer is complicated and may be different in different cancers." (PMID 28569838, 2017). "Targeting USP13 in this subset of cancer may re-sensitize cancer to platinum or PARPi treatment." (PMID 28569838, 2017). "USP13 interacts with FASN to enhance its protein stability to promote fatty acid synthesis, cancer stemness and sphere formation." (PMID 40621620, 2025). "Hence, inhibition of USP13 might be beneficial for related cancer treatment." (PMID 35445009, 2022). "HAUSP/USP7, USP10, USP11, USP13, OTUD3, and Ataxin-3 have all been recently identified as PTEN DUBs that control PTEN activity in different cancer-specific contexts." (PMID 36385557, 2022).
cancer (continued). "USP13 enhanced metastasis and ascites development in GEMM and increased cancer cell migration, 3D-spheroid forming efficiency, and tumorigenesis in syngeneic mice." (PMID 35173307, 2022). "To detect the role of USP13-FASN axis in regulating cancer stemness and lipogenesis in SCLC, we stably depleted FASN after WT USP13 reconstitution in USP13 knockdown cells." (PMID 35898882, 2022). "The positive feedback between USP13 and RAP80 is of great significance for genomic stability in normal cells, whereas it promotes cancer cells proliferation." (PMID 36188217, 2022). "In addition to its role in cell cycle regulation, DDR, myoblast differentiation, ER quality control and autophagy, USP13 is also involved in the pathogenesis and development of various pathological conditions, including infection, inflammation, fibrosis, neurodegenerative diseases and cancers." (PMID 36188217, 2022). "A high copy number of USP13 positively correlated with its mRNA expression in EOC and other cancers." (PMID 35173307, 2022). "E3 ubiquitin ligases (Mule, SCFβ-TrCP, SCFFBW7, TRIM17, APC/CCdc20, and FBXO4) and deubiquitinases (USP9X, Ku70, USP13, JOSD1, and DUB3) work together to balance MCL1 stability, which has an important role in the chemoresistance of cancer cells." (PMID 33803505, 2021). "TCI identified 6 such SGA-FIs, including some well-known cancer drivers, such as PTEN and NEFH, and potential cancer drivers mentioned in recent studies, such as TLK2, USP13, and PIM3." (PMID 31276486, 2019). "This is in consistent with previously reported findings that USP13 deubiquitinates and stabilizes PTEN protein thus suppresses tumorigenesis in human cancers." (PMID 31200745, 2019). "USP13 upregulates ACLY and OGDH, two key regulators that drive glutaminolysis, ATP generation and lipid synthesis in cancer metabolism." (PMID 27892457, 2016). "This highlights the potential therapeutic value of targeting USP13 and ACLY in cancer treatment." (PMID 41330897, 2025). "USP13, belonging to the DUB family, has an important effect on the oncogenesis of various cancers." (PMID 40746889, 2025). "Considering that USP13 and USP10 also have the role of regulating substrate deubiquitination and inhibiting the degradation of substrate ubiquitin proteasome, and are also widely involved in life processes such as cancer and cell apoptosis." (PMID 39517125, 2024). "In addition, further exploring the mechanism by which USP13 is regulated in various tumors and identifying downstream substrates of USP13 may provide new perspectives for future research, and we expect USP13 to be a novel target in the prevention and treatment of cancers." (PMID 36188217, 2022). "In vitro and in vivo depletion of USP13 inhibited SCLC cancer stem cells (CSCs) properties and tumorigenesis, and this inhibitory effect was rescued by reconstituted expression of wide type (WT) USP13 but not the enzyme-inactive USP13 mutant." (PMID 35898882, 2022). "Therefore, our data demonstrate that USP13 is a novel regulator of MCL1 stability and a potential therapeutic target for cancer treatment." (PMID 29335437, 2018). "Since USP13 deubiquitinates RAP80 and regulates DDR, we next examined the role of USP13 in cancer." (PMID 28569838, 2017). "Interestingly, NEDD4-1 undergoes auto-ubiquitination that serves it as a scaffold for engaging the ubiquitin-specific protease 13 (USP13) to form a NEDD4-1/USP13 deubiquitination complex, which subsequently deubiquitinates and stabilizes VPS34 to induce phagophore nucleation in cancer cells." (PMID 36918822, 2023). "Given the significance of USP10, USP11, USP13 and OTUD3 in PTEN stability, the development of a potent PTEN activation approach through manipulation of these DUBs may represent an attractive strategy for cancer prevention and treatment." (PMID 36385557, 2022).
cancer (continued). "Therefore, we propose that deubiquitinase USP13 is a new regulator of MCL1 stability and drug sensitivity to BH3 mimetic inhibitors, and may represent a promising therapeutic target for cancer treatment." (PMID 29335437, 2018). "Knocking out USP13 did not affect cancer cell growth in vitro and in vivo." (PMID 28569838, 2017).
infection (8 papers, 2017 to 2025). The state of being infected such as from the introduction of a foreign agent such as serum, vaccine, antigenic substance or organism. "The usp13 (cpxP) is an essential regulator of cell membrane stress in bacteria during host infection." (PMID 30546354, 2018). "Upon infection with DNA viruses, the majority of USP13-interacting STING is disassociated from USP13 and translocates to form puncta, thereby leading to increased ubiquitination of STING and boosted recruitment of TBK1." (PMID 28534493, 2017). "72-hours after the infection, the investigators observed cell death and/or growth reduction in all the CNS tumor lineages, although infection of DAOY was less pronounced when compared to USP13-MED and USP7-ATRT." (PMID 39347716, 2024). "Performing ProcartaPlex ELISA assays, we assessed whether the soluble TNF factors of these pathways (TNF-alpha, TNFSF9 and TNFRSF9) were secreted following infection and observed significantly increased secretion of TNF-alpha and TNFRSF9 from both USP7 and USP13 cells at 48 hpi." (PMID 40240536, 2025). "We also observed that a portion of USP13 was colocalized with STING at the ER without infection and HSV-1 infection resulted in STING disassociation from USP13 and redistribution in the cytoplasm, consistent with previous observations that STING migrates out of ER after HSV-1 infection." (PMID 28534493, 2017).
neurodegenerative disease (4 papers, 2021 to 2025). A disorder of the central nervous system characterized by gradual and progressive loss of neural tissue and neurologic function. "This dual effect propels USP13 into the spotlight as a potential therapeutic target, hinting at the prospect of USP13 inhibitors as novel interventions in the intricate tapestry of neurodegenerative diseases." (PMID 39840724, 2025). "The elucidation of USP13's regulatory mechanisms in neurodegenerative diseases highlights its potential as a target for therapeutic intervention." (PMID 39840724, 2025). "Collectively, due to its role in a variety of tumors and neurodegenerative diseases, USP13 has emerged as a potential therapeutic target for diverse tumors." (PMID 35445009, 2022). "Collectively these findings suggest that USP13 is a therapeutic target in neurodegenerative diseases." (PMID 34564439, 2021). "The data suggest that novel USP13 inhibitors improve neurodegenerative pathology via antagonism of de-ubiquitination, thus alleviating neurotoxic protein burden in neurodegenerative diseases." (PMID 34564439, 2021). "Furthermore, recent studies have shown that derivatives of spautin-1 display better USP13 inhibition and the ability to cross the blood-brain barrier, which is presumably beneficial for research on USP13-related neurodegenerative disease." (PMID 35445009, 2022). "Collectively, these findings suggest developing novel, specific USP13 inhibitors may be a strategy to prevent and treat neurodegenerative diseases such as AD and PD." (PMID 36188217, 2022). "In this aspect, inhibiting USP13 may lead to autophagy reduction to some extend and the efficacy of USP13 inhibition in models of neurodegenerative diseases should be carefully assessed." (PMID 36188217, 2022). "USP13 inhibition via our novel analogues may provide balance of ubiquitination and de-ubiquitination for toxic protein degradation in neurodegenerative diseases." (PMID 34564439, 2021). "Collectively, above limited but seminal studies suggest that interventions targeting other DUBs such as USP13 and USP14 could serve as a promising therapeutic strategy for neurodegenerative diseases, including PD and AD." (PMID 39840724, 2025).